ESR1 (estrogen receptor 1)
Diseases named in the same sentence as ESR1 in open-access papers (continued):
Sharing a sentence is not in itself a finding about the gene and the disease.
tumor (continued). "Notably, canonical breast cell differentiation genes and molecular markers (KRT8, KRT18, KRT14, TP63, ERBB2, ESR1, PGR) were not differentially expressed, suggesting the cells maintain their differentiation state and tumor subtype." (PMID 34741115, 2021). "Moreover, the expression levels of the CAT, ESR1, and KLKB1 genes were significantly correlated with the HCC stage (P < 0.05), while MMP9 was not significantly correlated with the tumor stage." (PMID 34671598, 2021). "The mean expression of ESR1 in tumours showing pCR after NAC was 34.13 ΔCt (IQR: 2.32 ΔCt, median: 34.36 ΔCt (min: 30.77 ΔCt, max: 40.01 ΔCt)), tumours without pCR had a mean expression of ESR1 of 33.81 ΔCt (IQR: 1.58 ΔCt, median: 34.44 ΔCt (min: 19 ΔCt, max: 37.05 ΔCt))." (PMID 34073233, 2021). "We propose that there may be an association between expression of GREM1 and lack of expression of the estrogen receptor, ESR1, as we only found GREM1 expression among the ESR1 negative tumor cells." (PMID 31694641, 2019). "In contrast, 5 of the 20 clear cell tumours examined were negative for both GREB1 and ESR1." (PMID 29973689, 2018). "Thus, the impact of TCC on RNA relative quantification is gene-specific and as far as MammaTyper® genes ERBB2, ESR1, PGR and MKI67 are concerned the bias introduced by the inclusion of tissue surrounding the invasive tumor appears to be non-critical." (PMID 30342538, 2018). "In addition, GJA1 does not vary directly with ESR1 and HER2 mRNA and protein levels but shows a stronger correlation with PGR mRNA and PR protein in tumor samples." (PMID 29495625, 2018). "However, in line with our data two studies found a frequent expression of ESR2 but not ESR1 in HNSCC cell lines and tumor tissues, suggesting a more prominent role of ESR2-related signaling." (PMID 28166815, 2017). "In multiple imputation with 100 imputed data sets at 5% significance level, ESR1 repeated the prognostic findings of DFS only, but not OS, while the complex partitioning parameter Stage_Site_tumour mIS repeated the findings of DFS, OS (results shown in S1 Statistical Analyses)." (PMID 25970543, 2015). "Two of the 31 most differentially expressed genes between the ESR1-negative and ESR1-positive BRCA1 tumours, CD133 and MMP7, were evaluated by immunohistochemistry and immunofluorescence in an independent series of 15 BRCA1 tumours, previously classified as basal or luminal." (PMID 19826428, 2009). "Two main groups were identified, one over-expressing markers typically found in sporadic luminal tumours such as GATA3, TFF1 and SCUBE2, and the other negative for ESR1, ERBB2 and the PR gene (PGR) (triple negative) and over-expressing genes from the basal layer such as CDH3, CRYAB and KRT5-17." (PMID 19826428, 2009). "Similarly, using the BioKey scRNA-Seq dataset, almost no overlap between MHC-I and ESR1 expression was observed, and the comparison between ER– and ER+ cells in the same patient showed higher expression of the MHC-I genes in the ER– tumor compartment." (PMID 41289011, 2026). "mRNA levels of ESR1 and PGR had bimodal distributions, suggesting there may be a clear discrimination between patients with hormone receptor-positive and receptor -negative tumours at the mRNA level." (PMID 38587062, 2024). "Along with the activation of JNK signalling in tumour without CDK6 amplification with combination therapy, the absence of ERK signal further reflects the transition to an endocrine independent resistance state, with reduced reliance on the interaction of ESR1/ERK." (PMID 35800379, 2022).
tumor (continued). "Notably, correlation analysis revealed a significant correlation between expression levels of ESR1 and GATA3 in non-cancerous tissues despite lack of correlation in tumor tissues, suggesting the impact of cancer development on the functional association between these two genes." (PMID 34094972, 2021). "Furthermore, tumours that did not exhibit a Ki67 response following preoperative endocrine therapy were enriched for genomic drivers of endocrine resistance, such as FGFR1 and CCND1 amplification, as well as intrachromosomal ESR1 fusions and enhanced E2F-mediated transcription." (PMID 33671468, 2021).
cancer (2,837 papers, 2002 to 2026). A tumor composed of atypical neoplastic, often pleomorphic cells that invade other tissues. "Over 59% of the PRAEGNANT cohort comprised patients with HR+/HER2- cancer, likely all having undergone some form of endocrine treatment; 21% of patients in this subgroup tested positive for actionable ESR1 mutations." (PMID 39839709, 2025). "Using next-generation sequencing (NGS) data from a large pan-cancer cohort of almost 6000 patients from two German institutes of pathology, we determined the frequency and localization of ESR1 mutations across various cancer entities." (PMID 40282442, 2025). "The role of ESR1 polymorphisms in carcinogenesis and progression is still under investigation, but it has been identified as a candidate gene for cancer susceptibility." (PMID 40864066, 2025). "The median PFS was 4.8 months (95% CI, 3.5–7.1) overall and 5.6 months (95% CI, 4.8–NE) among patients with cancers with ESR1 mutations." (PMID 40598566, 2025). "Epidemiological studies were conducted to assess the association of the ESR1 PvuII polymorphism with the risk of cancer." (PMID 40429755, 2025). "Network-based interactome analysis identified PIK3R1, SRC, and ESR1 as highly connected nodes within cancer-associated signaling networks." (PMID 40649280, 2025). "The CBR was 19.2% (95% CI, 6.6–39.4) in all evaluable patients who received 60 mg/day palazestrant (n = 26) and 23.1% (95% CI, 5.0–53.8) among the 13 patients with cancers with ESR1 mutations." (PMID 40598566, 2025). "Research indicates that ESR1 mutations can enhance the adhesive properties of cancer cells, facilitating their colonization in bone tissue." (PMID 40075655, 2025). "Elacestrant is an FDA and EMA approved oral medication that targets cancer cells in ESR1 positive tumors, offering patients with these mutations a therapeutic opportunity." (PMID 40282442, 2025). "In patients with cancers with ESR1 mutations treated at the R2PD, the median PFS was 5.6 months (95% CI, 4.8-NE), and the 6-month PFS rate was 47%." (PMID 40598566, 2025). "Elacestrant, which is a selective ER modulator (SERM) and SERD, does not completely shut down ER signaling due to being an partial agonist and was also more active in cancers harboring ESR1 mutations." (PMID 40598566, 2025). "At 120 mg/day, the median progression-free survival was 4.8 months (95% CI, 3.5–7.1) overall and 5.6 months (95% CI, 4.8–NE) among patients with cancers with ESR1 mutations." (PMID 40598566, 2025). "Palazestrant demonstrated a manageable safety profile, with antitumor activity observed in patients with heavily pretreated cancers with wild-type and ESR1-mutated BC." (PMID 40598566, 2025). "The CBR was 45.7% (95% CI, 33.7–58.1) in all evaluable patients who received 120 mg/day palazestrant (n = 70) and 58.6% (95% CI, 38.9–76.5) in patients with cancers with ESR1 mutations (n = 29)." (PMID 40598566, 2025). "ESR1 mutations promote constitutive ER activity and affect other signaling pathways, allowing cancer cells to proliferate by employing mechanisms within and without direct regulation by the ER." (PMID 38519482, 2024). "We identified cancer-associated nonsynonymous mutations in the LBDs of either ESR1 or PGR genes deposited in the cBioPortal for Cancer Genomics33,34." (PMID 38890276, 2024). "In the postoperative period, local ESR1 mRNA therapy and the associated ER expression improve all genomic functions in the residual breast tissue, inhibiting cancer recurrence." (PMID 39329990, 2024). "The high incidence of mutation “acquisition” was largely driven by the gain of ESR1 mutations, and likely reflects clonal selection in cancer, while emphasizing the importance of ctDNA liquid biopsy testing to match treatment to current genomics." (PMID 37982575, 2024).
cancer (continued). "ESR1 is a gene encoding estrogen receptor alpha, whose mutation is closely related to cancer, inflammation and other pathological processes." (PMID 38905418, 2024). "Collectively, our study warrants clinical investigation of the combination of a next-generation oral SERD with capecitabine in metastatic ER + BC, particularly in patients with cancers harboring an ESR1 mutation." (PMID 38851818, 2024). "We identify novel ESR1 mutations that alter F404, that occur only in patients treated with fulvestrant with preexisting activating ESR1 mutations in their cancer." (PMID 37982575, 2024). "In a second study, the same researchers observed that the upregulation of these miRNAs was inversely associated with the expression of ESR1 target mRNA and progressive loss of ERα immunoexpression and that these patterns were associated with malignant tumors." (PMID 38954129, 2024). "In this study, we employed cancer cell models engineered to harbor ESR1 mutations (MCF7Y537N/Y537S), as well as an external set of mutated T47D (Y537S mutation)." (PMID 38519482, 2024). "Aside from AR, another top TF in Black men, ESR1 (estrogen receptor alpha), is a sex steroid hormone receptor implicated in hormone-driven cancers, such as prostate and breast." (PMID 39044302, 2024). "Further mutations in luminal NST carcinomas involve genes such as ESR1, (especially a progression mutation after hormonal therapy), FGFR1, MDM4, AKT1, and GATA3." (PMID 38015260, 2024). "For instance, fulvestrant or selective ER degraders are often recommended for ESR1-mutated cancers because ESR1 mutation is considered a marker of resistance to aromatase inhibitors (AI)." (PMID 37377606, 2023). "In the dog, the ESR1 gene encodes for ERα in the mammary gland, and a reduced gene expression observed in malignant tumors here closely reflects reduced ERα immunoexpression." (PMID 36978627, 2023). "cfDNA was extracted from the blood samples of patients with hormone receptor-positive breast cancer, and ESR1 mutations were identified by NGS using the Oncomine pan-cancer cell-free assay." (PMID 37370935, 2023). "The genetic alterations in T47D and MCF7 cancer cells with ESR1 mutations have resulted in the resistance to fulvestrant, raloxifene, and 4-Hydroxytamoxifen (4-OHT) drugs under in vitro conditions." (PMID 35879772, 2022). "Mutations of ESR1, the gene encoding the estrogen receptor alpha, are associated with acquired resistance to therapy in luminalbreast cancer." (PMID 35440136, 2022). "ESR1 is a frequently mutated cancer gene, in particular in metastatic breast cancer, and was identified among the top 100 important features by the XGBoost model." (PMID 35106465, 2022). "The genes MAPK14, HSP90AA1, PTGS2, and ESR1 have been linked to cancer, infection, and immune disease." (PMID 36212968, 2022). "According to the cBioPortal cancer genomics database, ESR1 mutations have been detected in 4–6% of uterine corpus endometrial carcinoma samples." (PMID 35954453, 2022). "The NGS analyses identified mutations in eight cancer associated genes: ESR1, MECOM, JAK3, KMT2C, CTNNB1, CALR, NCOR1 and AMER." (PMID 34209696, 2021). "NGS analysis of nine individual CTCs identified three different CNV profiles and mutations in eight cancer associated genes, including a potentially resistance-associated ESR1 mutation." (PMID 34209696, 2021). "Treatment interferes with clonal evolution and selection of subclones in BC as has been obvious from ESR1 mutation which is far more frequent in previously AI‐treated luminal cancers than in treatment‐naïve cases." (PMID 34779146, 2021).
cancer (continued). "Comparing all mice carrying at least one Esr1 allele (Esr1 +/− and Esr1 WT) to Esr1 KO mice yields a difference in carcinoma incidence of 62.4% vs 95%, which is significant (p < 0.027)." (PMID 34068249, 2021). "Recently, using a BC cell line model, it was demonstrated that, in a hormone-free cancer cell, when a decreased PR expression is induced, ESR1 also showed a decreased expression associated with a hypermethylation of the ESR1 promoter." (PMID 33316872, 2020). "In total, the sum of contribution coefficients of the liver samples in Patient 1 was 0.86 and this was corroborated with the ESR1 mutation being present in an estimated 98% of cancer cells that shed DNA in the plasma." (PMID 32221288, 2020). "ChIP-seq analysis of H3K27Ac in MCF-7 cells indicated that the SE-targeted ESR1 gene encodes only estrogen receptor alpha (ERα); furthermore, this oncogenic transcription factor can distinguish cancer subtypes through distinct signaling pathways." (PMID 32382065, 2020). "Since ERα is overexpressed and the ESR1 gene is mutated in the ER+ cancer tissues, degradation of ER was considered an alternate and more specific treatment option." (PMID 32824207, 2020). "ESR1 mutations rarely exist in primary tumors (~ 1%) but are relatively common (10–50%) in metastatic, endocrine therapy-resistant cancers and are associated with a shorter progression-free survival." (PMID 32014063, 2020). "A study of ~6000 cancer patients reported a strong risk signal for endometrioid cancers was located in a promoter of ESR1." (PMID 31778358, 2020). "Previously, we and others showed that the gene encoding ER (ESR1), to which cancer cells are transcriptionally addicted, is critically upregulated during LTED adaptation." (PMID 31439835, 2019). "Translational studies of samples collected in TREnd are ongoing and will include ctDNA analysis to study the incidence of somatic mutations in a panel of cancer genes including ESR1 and their correlation with response to ET administered post study." (PMID 31142370, 2019). "We observed that ESR1 mutations were associated with higher values of SETER/PR (presumably because these mutations are constitutively activating), but only some cancers with higher values of SETER/PR index contained an ESR1 mutation." (PMID 31231679, 2019). "Pre-clinical studies of these drugs demonstrated efficacy in inhibiting cancer cell growth in models harboring ESR1 mutations." (PMID 31795152, 2019). "In contrast to this we show that patients with ESR1 mutations in their cancers have worse outcome on fulvestrant alone." (PMID 29497091, 2018). "They found ESR1 mutations rarely in women with any molecular subtype of cancer other than estrogen receptor-positive disease." (PMID 30083595, 2018). "The role of active ESR1 fusions in promoting EMT-like gene expression changes follows a pattern associated with other members from a diverse family of cancer-associated gene fusion events." (PMID 30089255, 2018). "ESR1 mutation sub clonality means they are poorly representative of a patient’s cancer overall, limiting the potential for their ctDNA dynamics to predict clinical outcome." (PMID 29497091, 2018). "The remainder of the drug candidates identified in association with ESR1 and RA are most commonly used in the treatment and prevention of estrogen receptor positive cancers." (PMID 26156520, 2015). "As the total cancer risk of an individual is probably a result of risk alleles at multiple loci, we evaluated the combined effect of the risk haplotypes of the two ESR1 LD blocks compared to the protective haplotypes." (PMID 23574728, 2013). "In the present survey, we studied SNPs in known cancer-associated genes and observed significant differences in allele and haplotype frequencies for the ESR1 gene in the ESS material." (PMID 23574728, 2013).